PABPC1L2B (poly(A) binding protein cytoplasmic 1 like 2B)
Synonyms: RBM32B
Tractability: PROTAC: ubiquitination databases record sites on it.
Gene: Protein-coding gene on chromosome X (73,002,939 to 73,006,106, forward strand). Ensembl gene ENSG00000184388.
Gene Ontology:
Molecular function: mRNA 3'-UTR binding; poly(U) RNA binding; nucleic acid binding; poly(A) binding; RNA binding
Cellular component: extracellular exosome; cytoplasmic stress granule; cytosol; nucleus; ribonucleoprotein complex
Homologues: Orthologues: chimpanzee PABPC1L2B (100% identical), macaque PABPC1L2B (100% identical), dog PABPC1L2A (99% identical), mouse Pabpc1l2a (94% identical), mouse Pabpc1l2b (94% identical), rat Pabpc1l2a (93% identical), zebrafish pabpc1a (78% identical), zebrafish pabpc1b (78% identical). Paralogues in human: PABPC1L2A (100% identical), PABPC1 (80% identical), PABPC4 (76% identical), PABPC3 (72% identical), PABPC1L (70% identical), PABPC4L (62% identical), PABPC5 (58% identical), TARDBP (23% identical), SYNCRIP (22% identical), RBMS1 (19% identical), HNRNPR (18% identical), RBM34 (18% identical), and 12 more.
Diseases named in the same sentence as PABPC1L2B in open-access papers:
PABPC1L2B is named in the same sentence as 1 disease in open-access papers, as found by Europe PMC text mining. Sharing a sentence is not in itself a finding about the gene and the disease.
PABPC1L2B shares sentences with these, for which no sentence is quoted: glioma (1 paper).